CD4 (CD4 molecule)
Diseases named in the same sentence as CD4 in open-access papers (continued):
Sharing a sentence is not in itself a finding about the gene and the disease.
esophageal squamous cell carcinoma (20 papers, 2018 to 2025). Esophageal squamous cell carcinoma (ESCC) is a type of esophageal carcinoma (EC) that can affect any part of the esophagus, but is usually located in the upper or middle third. "For example, one recent study revealed that TRAV39 expression was associated with memory CD4 T cell activation in Esophageal Squamous Cell Carcinoma." (PMID 36987861, 2023). "In our esophageal SCC series, a higher CD4+ T cells tumor infiltration was significantly associated to a better overall survival." (PMID 31429521, 2019). "RBM15 also modulates procollagen-lysine,2-oxoglutarate 5-dioxygenase 3 (PLOD3), enhancing tumor-infiltrating CD4+ T cell abundance in esophageal squamous cell carcinoma (ESCC), correlating with favorable prognosis in ESCC4." (PMID 40370450, 2025). "Correlation between CD4+CD25+FOXP3+ Tregs, CD8+TILs/CD4+CD25+FOXP3+ Tregs ratio, and clinicopathological characteristics in patients with esophageal squamous cell carcinoma (n = 126)." (PMID 39264227, 2024). "T. forsythia can induce pro-inflammatory cytokines such as IL-1β and IL-6 by CD4 + T helper cells and TNF-α in esophageal squamous cell carcinoma (ESCC)." (PMID 35847109, 2022). "Mouse models of esophageal squamous cell carcinoma (SCC) treated with cisplatin and 5- fluorouracil (5-FU) had increased percentages of intratumoral CD4 and CD8." (PMID 29502288, 2018). "In another study, the expressions of CD8+, CD4+, FOXP3+, Immunoglobulin G4 (IgG4), and IL-10 and clinical information of 118 patients with esophageal squamous cell carcinoma (ESCC) were assessed with hematoxylin and eosin (H&E), immunohistochemistry (IHC) staining and multi-color Immunofluorescence." (PMID 38077386, 2023). "Furthermore, tolerogenic DCs (tDCs) and exhausted CD4, CD8 T, and NK cells play a key role in immune-suppressed TME in esophageal squamous-cell carcinomas (ESCC)." (PMID 36291050, 2022). "Since 2003, how the interplay between CD4+ and CD8+ T cells strongly correlates with esophageal SCC patients' prognosis has been shown, but the crucial question now is whether the immune infiltrate could predict the outcome after the neoadjuvant therapy." (PMID 31429521, 2019). "We investigated the density, distribution and relationship of five immune markers CD4, CD8, Foxp3, IL-10 and IgG4 with multiple immunostaining method in 118 esophageal squamous cell carcinoma (ESCC) together with clinical data." (PMID 36891293, 2023). "Also, study reported that the prognostic risk score was positively correlated with CD4+ T content, but not B lymphocyte, CD8+ T, neutrophil, macrophage, and dendritic cell content, in patients with esophageal squamous cell carcinoma." (PMID 36685853, 2022).
extrapulmonary tuberculosis (20 papers, 2010 to 2025). A tuberculosis that occurs at body sites other than the lung. "We conducted a pilot case-control study to identify genetic variants associated with extrapulmonary tuberculosis in patients with previously characterized immune defects: low CD4+ lymphocytes and low unstimulated cytokine production." (PMID 20196868, 2010). "HIV infection is associated with an increased risk of extrapulmonary tuberculosis, and the risk increases as the CD4+ lymphocyte count declines." (PMID 20096113, 2010). "We considered strategies including and excluding WHO 4 extrapulmonary tuberculosis as a trigger for switching to ensure that our results regarding CD4 monitoring frequency were robust." (PMID 26316598, 2015). "Of these 49, 24 (49%) patients had pulmonary or extra-pulmonary tuberculosis prior to death and their baseline median CD4 count was 67 cells/μl (IQR: 42-107)." (PMID 21537095, 2011). "Those with less CD4 are more likely to develop extrapulmonary tuberculosis." (PMID 34277657, 2021). "In addition to CTX prophylaxis and baseline CD4+ cell count, patients who were diagnosed with extrapulmonary tuberculosis in the past three months also had a higher incidence of TM infection (aHR = 1.56, 95% CI 1.02–2.40, p = 0.04)." (PMID 31851879, 2019). "Two girls progressed to CDC classification C; one girl had esophageal candidiasis (age at onset was 2.1 years, CD4 at onset was 22%) and another girl developed extrapulmonary tuberculosis (age at onset was 10 years, CD4 at onset was 27%) during their follow-ups." (PMID 23181827, 2012). "We have previously noted subtle immunologic defects, such as low numbers of CD4+ lymphocytes and low unstimulated cytokine production, in HIV-seronegative adults with previous extrapulmonary tuberculosis." (PMID 20096113, 2010). "The patients with IRD at HAART initiation were younger, had low CD4+ T-cell count, low WBC count and higher proportion of extra pulmonary tuberculosis(EPTB) (P < 0.05)." (PMID 21176160, 2010).
gastric adenocarcinoma (20 papers, 2017 to 2025). "In gastric adenocarcinoma data, 19 of the 42 T cell markers were associated withC1GALT1 expression (available online), andC1GALT1 expression was positively correlated with the levels of infiltrating of CD4+ T cells and macrophages." (PMID 38807485, 2024). "CD4 + T cells and T follicular helper cells were likely to promote the maintenance of a protective immune response, which was related to the good prognoses of patients with gastric adenocarcinoma in the low-risk group." (PMID 34790582, 2021). "Schmee found that Helicobacter pylori produced gamma-glutamyl transpeptidase, which could inhibit CD4+ T cell proliferation and infiltration in the gastric mucosa, resulting in the development of peptic ulcer disease, gastric adenocarcinoma, and even mucosa-associated lymphoid tissue lymphoma." (PMID 36569910, 2022). "The TIMER algorithm demonstrated a significant positive correlation between UBR1 expression and CD4+ T-cell infiltration in stomach adenocarcinoma (STAD) (P < 0.05)." (PMID 39181686, 2024). "The TIMER database showed that the GPX8 expression level was positively correlated with infiltrating levels of CD8+ T cells, CD4+ T cells, macrophages, neutrophils, and dendritic cells in stomach adenocarcinoma." (PMID 35712475, 2022). "Future studies should concentrate on delineating the direct molecular biological mechanisms of these correlations and investigate the intercellular communications between the gastric adenocarcinoma cells and CD4+ TILs." (PMID 33469515, 2020). "High Notch3/4 expression was associated with high levels of infiltration of macrophage and CD4+ T cells in gastric adenocarcinoma." (PMID 32028262, 2020). "After adjusting the correlation for tumor purity, results demonstrated that the Notch mRNA expression level had significant correlations with TAMs, DCs, CD4+ T cells and neutrophils in gastric adenocarcinoma." (PMID 32028262, 2020). "Upregulation of ITGAL expression was strongly associated with immunomodulators, chemokines, and levels of CD8+ T cells, CD4+ T cells, B cells, monocytes, neutrophils, macrophages, T cells, natural killer (NK) cells, and myeloid dendritic cell infiltration in gastric adenocarcinomas (STAD)." (PMID 38646528, 2024). "Moreover, upregulated ITGAL expression was strongly connected with immunomodulators, chemokines, and infiltrating levels of CD8+, CD4+ T cell, B cell, monocyte, neutrophil, macrophage, T-cell regulatory, NK cell, and myeloid dendritic cell in stomach adenocarcinoma (STAD)." (PMID 35399517, 2022). "Immunohistochemistry (IHC) was utilized to assess PD-L1 expression and TIIC markers (CD3, CD4, CD8, CD19, CD31, CD68, CD11c, CD56, and α-smooth muscle actin) in gastric adenocarcinoma tissues from 268 patients." (PMID 38050283, 2023). "High expression of CXCL9 and CXCL10 correlated positively with infiltrating levels of CD4+ T and CD8+ T cells in stomach adenocarcinoma." (PMID 33323542, 2020). "Additionally, LAYN expression was positively correlated with the infiltration of CD4+T and CD8+T cells, macrophages, neutrophils, and dendritic cells in colon and gastric adenocarcinomas." (PMID 34098960, 2021). "Additionally, Notch1 had a positive correlation with CD4, GATA3 and STAT5B and a negative correlation with CD59 in gastric adenocarcinoma." (PMID 32028262, 2020).
glaucoma (20 papers, 2015 to 2025). Increased pressure in the eyeball due to obstruction of the outflow of aqueous humor. "Although evidence regarding CD4+ T cells in human glaucoma is limited, elevated serum levels of pro-inflammatory cytokines associated with CD4+ T cells have been reported." (PMID 38317227, 2024). "One mechanism of glaucoma autoimmunity is: High intraocular pressure directly causes optic nerve injury and induces CD4 T cell infiltration." (PMID 39076973, 2024). "In the recent year, there is new evidence suggesting that CD4+ T cells enter into the retina and cause neurodegeneration in the glaucoma model." (PMID 30877182, 2019). "We investigated if CD4+ T cells play a causal role in progressive neurodegeneration in glaucoma by adoptively transferring T cells from glaucomatous B6 mice into Rag1−/− mice." (PMID 30097565, 2018). "Our study provides novel insights into the role of peripheral CD4+ T cells in glaucoma pathogenesis, shedding light on the mechanisms underlying their infiltration into the retina and offering potential avenues for innovative therapeutic interventions in this sight-threatening disease." (PMID 38317227, 2024). "Investigating HIV as a risk factor for the development of glaucoma in younger to middle-aged patients will require further research to establish a relationship between CD4 count and viral load with optic nerve function in order to validate this hypothesis." (PMID 33141357, 2020). "Likewise, CD4+ T cells presented a greater stimulation response (threefold) in glaucomatous samples, together with proinflammatory cytokine secretion, proposing the T-cell subset imbalance as a candidate biomarker of autoimmune susceptibility in glaucoma." (PMID 34439995, 2021). "Specifically, we observed that the circulating CD4+ T cell response is enhanced in parallel with the progression of visual damage in glaucoma patients." (PMID 40440644, 2025). "Another significant finding in our study is the overactivation of peripheral CD4+ T cells in both human and experimental glaucoma, and developed Th1-biased responses." (PMID 38317227, 2024). "Firstly, we observed that CD4+ T cells from glaucoma patients displayed enhanced activation and a bias towards T helper (Th) 1 responses, which correlated with visual impairment." (PMID 38317227, 2024). "While a few studies have sporadically observed alterations in peripheral blood T cells in patients with glaucoma, the activation status of CD4+ T cells in glaucoma remains poorly understood." (PMID 38317227, 2024). "In experimental glaucoma models, including inducible and genetic mouse models, increased infiltration of CD4+ T cells into the retina has been observed." (PMID 38317227, 2024). "Taken together, existing evidence strongly supports the involvement of CD4+ T cells in the pathogenesis of glaucoma." (PMID 38317227, 2024). "Given the involvement of CD4+ T cells as well as the microbiota in the pathogenesis of glaucoma, it has been recently suggested that glaucoma should be included in the spectrum of autoimmune diseases." (PMID 34746029, 2021). "More recently, the analysis of T-cell subset distribution detected a glaucoma-related shift, since decreased frequency of CD4+ (or CD8+)/CD25+/FoxP3+ was determined in POAG patients when compared to controls." (PMID 34439995, 2021). "The frequency of IL-17A-secreting cells and IL-17A+ CD4 T cells is significantly higher in patients with glaucoma compared with controls." (PMID 33829024, 2021). "Recently, using mice deficient in CD4+ αβ T cells, it was reported that CD4+ T cells play a crucial role in propagating RGC degeneration, particularly during the prolonged period of progressive neural damage, in glaucoma." (PMID 32117239, 2020). "Patients with glaucoma exhibited a trend of decreased frequency of Treg and their CD4+ T cells presented a greater stimulation response characterized by increased proliferation and proinflammatory cytokine secretion." (PMID 32117239, 2020).
glaucoma (continued). "Identification of CD4+ T-cell responses in glaucoma opens the possibility of targeting T cells in the retina as a treatment to halt the progressive RGC and axon degeneration and vision loss." (PMID 30097565, 2018). "Similarly, in the glaucoma disease model, β7+CD4+ T cells accumulated in the gut prior to retina and inhibition of gut entry impeded their subsequent retinal infiltration." (PMID 40709181, 2025). "Moreover, the ratio of EM CD4+-to-CM CD4+ (EM/CM) was notably higher in glaucoma patients, indicating a transformation of CD4+ T cells from a " quiescent" to a " primed for action" state." (PMID 38317227, 2024). "Additionally, glaucoma was induced in mice with CD4-specific expression of Tomato, and immunofluorescence staining using anti-CXCR3 antibodies demonstrated a significant presence of CXCR3+ CD4+ T cells within the retina." (PMID 38317227, 2024). "Through the lens of both peripheral immunity and the BRB, our findings unveil a novel perspective on how peripheral CD4+ T cells contribute to the pathogenesis of glaucoma and provide an opportunity to develop innovative strategies for intervening in this blinding disease." (PMID 38317227, 2024). "EM CD4+) among total CD4+ T cells in glaucoma patients, alongside a significant decrease in Freq." (PMID 38317227, 2024). "(i) The mechanisms by which EIOP affects circulating CD4+ T cell biology and function in the early phase of glaucoma remain largely unknown." (PMID 38317227, 2024). "Similar result was found for increased numbers of CD4 (+) CD25 (+) T-cells in glaucoma patients." (PMID 37124610, 2023). "Similarly, the RNFL area was reduced in glaucoma eyes and high and low CD4 groups as compared to the seronegative controls." (PMID 26258547, 2015). "Moreover, RD and glaucoma shared certain pathogenesis characteristics, including the involvement of CD4 T-cells and microbiota, thus the presence of RA may increase the possibility of glaucoma development." (PMID 34362122, 2021). "In order to gain deeper insights into the involvement of CD4+ T cells in glaucomatous retinal neurodegeneration, we established an EIOP-induced glaucoma model characterized by an approximately 28-day EIOP period followed by prolonged RGC loss." (PMID 38317227, 2024). "From the perspective of the fold changes of immune cell components, the CD8+ T cell, CD4+ memory T cell, monocytes, macrophages, M1 and dendritic cell components of POAG individuals are significantly different from those of non-glaucoma individuals." (PMID 34926471, 2021). "Studies have shown that CD4+ T cells can facilitate RGC death, and an imbalance in Treg cells/T17 cells has been observed in experimental autoimmune optic neuritis, a condition sharing similarities with glaucoma." (PMID 38892444, 2024). "In addition to high intraocular pressure, antibodies, CD4 T cells, and heat shock protein (HSP) produced by the microbiome may be the pathogenesis of glaucoma." (PMID 39076973, 2024). "Thus, unraveling the functional changes of circulating CD4+ T cells and the BRB, as well as the mechanisms enabling circulating CD4+ T cell invasion into the retina, represents the key to understanding the etiology of glaucoma." (PMID 38317227, 2024).
hyperthyroidism (20 papers, 2007 to 2026). Overactivity of the thyroid gland resulting in overproduction of thyroid hormone and increased metabolic rate. "Cluster 1 cells from patients with TED showed elevated expression of CD4+ T cell markers, aligning with findings from a previous study that identified CD4+ T cells associated with hyperthyroidism and TED." (PMID 39704170, 2024). "At the multivariate regression logistic analysis, only T CD4+ cell nadir <200 cell/mm3 was independently associated with hyperthyroidism symptomatic disorders (OR = 3.08, 95% CI 1.06–1.45; p = 0.005)." (PMID 31857648, 2019). "As a matter of fact, we found that a T CD4+ cell nadir <200 cell/mm3 was independently associated with symptomatic hyperthyroidism." (PMID 31857648, 2019). "Comparing the hyperthyroidism group with the healthy controls revealed significant differences in the following immune cell types: naive B cells, monocytes, naive CD4+T cells, and Tregs." (PMID 39872521, 2024). "The level of the pro-inflammatory markers (TNF-α, IL-1, IL-4, IL-6, and IL-10) in the hyperthyroidism group of rats was much higher than that of the healthy animals, whereas the level of the apoptotic marker (CD4+) was noticeably lower." (PMID 37020549, 2023). "Moreover, the increase of CD4+ cells, which indicates hyperactivation of T helper subset, could also promote the maturation of pathogenic plasma cells from B lymphocyte, thus exacerbating the hyperthyroidism in GD." (PMID 27721890, 2016). "In GD, activated CD4+ T cells secrete cytokines/chemokines that stimulate B-cells to produce TRAb, and in turn hyperthyroidism occurs." (PMID 27602020, 2016). "The activated CD4+ T cells secrete cytokines/chemokines that stimulate B-cells to produce TSAb, and in turn hyperthyroidism occurs." (PMID 27602020, 2016). "In group C, four participants withdrew during Step I because of intolerance to IL-2 injections, one withdrew during Step II because he/she wanted to restart HAART, two were terminated because of the development of hyperthyroidism, and one was terminated because of low CD4+ T cell concentrations." (PMID 17260026, 2007). "In this case, the onset of hyperthyroidism after ART initiation and rising CD4 count strongly favored an IRIS mechanism." (PMID 41551367, 2026). "Interestingly, treatment of hyperthyroidism-modeled group with hesperidin therapy dramatically decreased blood levels of TNF-α, IL-1, IL-4, IL-6, and IL-10 while sharply increasing CD4+ level close to healthy controls." (PMID 37020549, 2023). "The findings showed that hesperidin significantly modulated hyperthyroidism deteriorations, this was evidenced by a remarkable decline in serum T4, FT4, T3, FT3, TNF-α, IL1β-, IL4-, IL-6, and IL-10 levels, with a minor increase in TSH and significant raise in CD4+ level." (PMID 37020549, 2023).